MCM10 (minichromosome maintenance 10 replication initiation factor)
Diseases named in the same sentence as MCM10 in open-access papers (continued):
Sharing a sentence is not in itself a finding about the gene and the disease.
cancer (34 papers, 2009 to 2025). A tumor composed of atypical neoplastic, often pleomorphic cells that invade other tissues. "Our study also found that MCM10 has diagnostic value in most cancer types, particularly in CESC, CHOL, and GBM." (PMID 37848534, 2023). "Further research demonstrated that MCM10 is strongly linked to immune cell infiltration, immunological subtypes, and molecular subtypes in several cancers." (PMID 37848534, 2023). "The mutational landscape of MCM10 in pan-cancer is shown in our work, along with a landscape of connection with copy number variation and methylation." (PMID 37848534, 2023). "The frequency of MCM10 modifications (mutations and CNAs) in 32 TCGA cancer types was examined using the cBioPortal program to analyze the mutational landscape of MCM10 in human malignancies." (PMID 37848534, 2023). "We also evaluated the strength of the association between TMB or MSI and MCM10 expression in pan-cancer." (PMID 37848534, 2023). "Elevated MCM10 levels are associated with poor prognosis in cancer patients, but a redox-related upstream control has not been described." (PMID 35063803, 2022). "Interfering with Cytotoxic T lymphocyte (CTLA-4) and ProgrammedDeath-1 (PD-1) reportedly has clinical benefits in several human cancers, so the characterizing associations between MCM10 and immune checkpoints will potentially enhance OV treatment." (PMID 35664337, 2022). "In cervical and urothelial cancers, high expression of MCM10 has been associated with a higher grade cancer or malignant cancer." (PMID 30135378, 2018). "Cancer immune and molecular subtype were shown to be substantially linked with MCM10 expression." (PMID 37848534, 2023). "Considering the close relationship between MCM10 and various malignant tumours, we believe that MCM10 may also be associated with the development of UCEC and can be an effective prognosis biomarker." (PMID 37246638, 2023). "However, MCM10 is known to be associated with pathological DNA replication, and it has been implicated in multiple cancers, like breast and prostate." (PMID 33604163, 2021). "Noticeably, whether MCM10 plays a causal role in cancer cells proliferation, migration or genome instability is an interesting issue, which should be further interrogated." (PMID 34185429, 2021). "In addition, in consistent with results in ESCC, the significant associations between high expression of MCM10 and the poor survival outcomes were observed across multiple cancer types." (PMID 34185429, 2021). "Prior investigations of MCM10-associated disease have primarily focused on cancer development." (PMID 33712616, 2021). "MCM10 was determined as one of the top-ranked genes that is enriched in cancer-associated pathways." (PMID 30135378, 2018). "In addition to transcriptional changes, analyses of cancer genomes have identified chromosomal amplifications, deletions and mutations in MCM10." (PMID 28218679, 2017). "However, MCM10 association with genomic instability, cancer development and its relevant mechanisms remain unknown." (PMID 35813483, 2022). "The observations underscore the complex interplay between MCM10, telomerase, and telomere maintenance mechanisms in cancer cells." (PMID 38763334, 2024). "For example, mini-chromosome maintenance protein 10 (MCM10) strongly compensated for DNA replication pressure and promoted genome replication in S-phase cancer cells, which was more pronounced in cancer stem cell-like cells (CSC)." (PMID 38170222, 2024). "We further wanted to see if the protein expression correlates with the mRNA expression levels, and our qRT-PCR data confirms that MCM10 expression indeed corresponds with the aggressive cancer phenotype." (PMID 39086679, 2023). "The relationship between MCM10's DNA methylation and its mRNA expression in pan-cancer was then examined." (PMID 37848534, 2023). "The connection between MCM10 expression and particular immune cell infiltration in human cancer was also investigated." (PMID 37848534, 2023).
cancer (continued). "MCM10 expression was significantly higher in the case of the more aggressive cancer cell line HeLa compared to controls." (PMID 39086679, 2023). "To further explore the response of MCM10 to cancer immunotherapy, we analyzed the immunotherapy cohort data IMvigor210 and showed that high MCM10 expression was more efficacious for PD-L1 treatment." (PMID 37848534, 2023). "In fact, the number of activated origins in cancer cells, is statistically larger than in normal cells, which suggests that origin usage flexibility increases in cancer cells and molecules like MCM10 are needed to activate additional origins of replication." (PMID 39086679, 2023). "As a result, more experimental research is still required to ascertain if MCM10 can be used as a target for cancer therapy." (PMID 37848534, 2023). "The findings demonstrated that MCM10 expression was significantly and favorably linked with CNV in the majority of cancer types." (PMID 37848534, 2023). "Analysis of the data from the CancerSEA database suggested us that MCM10 expression was significantly associated with the biological processes of cell cycle, DNA damage and repair, and EMT in the 13 cancers in the figure." (PMID 37848534, 2023). "We first looked into the protein levels to understand if MCM10 expression correlated with the aggressiveness of cancer." (PMID 39086679, 2023). "Then, using the TISDB database, we examined the expression of MCM10 in distinct cancer immune and molecular subtype." (PMID 37848534, 2023). "The quantitation of the fluorescence intensity indicates that MCM10 intensity increases with the aggressiveness of cancer." (PMID 39086679, 2023). "We investigate the impact of MCM10 in human cancers by analyzing data from databases like the Gene Expression Profiling Interaction Analysis (GEPIA2), Genotype-Tissue Expression (GTEx) and The Cancer Genome Atlas (TCGA), among others." (PMID 37848534, 2023). "MCM10 is a key molecule that promotes initiation of DNA replication by origin unwinding and we wanted to investigate the expression of MCM10 in cancers." (PMID 39086679, 2023). "MCM10, therefore, can serve as a prominent biomarker for cancer progression and thus aid in early detection to control the spread of cancer cells." (PMID 39086679, 2023). "A pan‐cancer analysis based on GEPIA database showed that MCM10 mRNA expression was overexpressed in UCEC as compared with normal endometrium." (PMID 37246638, 2023). "Unfortunately, the role of increased expression of MCM10 during pre-replication is least understood, despite overexpression of MCM10 expression has been reported in various cancers." (PMID 35813483, 2022). "Based on the close relationship between MCM10 and various malignant tumors, we have reasons to believe that MCM10 is a potential prognostic marker." (PMID 35664337, 2022). "As a next step, we compared MCM10 expression in multiple cancer tissues, cancer cell lines versus normal tissue and normal cell lines respectively." (PMID 35813483, 2022). "Cumulatively these results provided direct evidence that MCM10 expression can up-regulate DDR during early stages of cancer and involve in BC progression." (PMID 35813483, 2022). "DNA replication initiation protein MCM10 has been previously observed to have an increased expression in different cancer subtypes." (PMID 35813483, 2022). "In cancer cells, knocking down MCM10 has been observed to increase S and Early G2 cells due to incomplete replication initiation." (PMID 35813483, 2022). "We corroborate this using Oncomine, which shows that there is an average of 2.9-fold increase in MCM10 in cancer samples compared to normal tissues." (PMID 33604163, 2021). "MCM10 RNA expression is high in a variety of cancer cell lines, with A549 cells demonstrating a much higher level of normalized expression (NX) than the pulmonary epithelial cell line HBEC3 (15.3 vs. 8.3)." (PMID 33604163, 2021).
cancer (continued). "The multiple properties of MCM10 are concordant with cell cycle surveillance and thus dysregulation of MCM10 is considered as a common molecular marker of cancer." (PMID 31952107, 2020). "Consistent with expression studies, cancer genome analyses reveal that the majority of chromosomal changes are gene amplifications, whereas MCM10 is rarely deleted." (PMID 31409229, 2019). "Up to this point, it is interesting to note that in both cell lines, MP-HX downregulated all six top-ranked genes (PLK1, MCM2, MCM3, MCM7, MCM10 and SKP2) that were proposed to be cancer-associated (Wu, Zhu & Zhang, 2012)." (PMID 30042885, 2018). "Targeting MCM10 also plays an important role when using anti-cancer agents such as platinum based drugs, 5-fluoro uracil, etc., which bind to DNA forming DNA lesions." (PMID 30135378, 2018). "It is interesting to note that all six top-ranked genes proposed to be cancer-associated (PLK1, MCM2, MCM3, MCM7, MCM10 and SKP2) were downregulated by MP-HX in both cell lines." (PMID 30042885, 2018). "Knockdown of MCM10 expression in the cancer cell line showed significantly decreased tumorigenic properties such as cell proliferation, migration and anchorage independence." (PMID 30135378, 2018). "Genetic amplification and/or overexpression of MCM10 are common in cancer, and can serve as a strong prognostic marker of poor survival." (PMID 28218679, 2017). "Given the elevated Mcm10 levels and frequency of genomic amplifications observed in cancer cells, it seems reasonable to propose that during oncogenesis cells rely on increased Mcm10 levels to ameliorate replication stress and drive cell cycle progression." (PMID 28218679, 2017). "Contrary to this idea, MCM10 has been proposed to be part of a group of high-priority genes that promote cell cycle related processes in cancer cells." (PMID 28218679, 2017). "MCM10 is a turnkey of the MCM complex in cancer proliferation, making it a strong target for anticancer therapy." (PMID 27780919, 2016). "We found that MCM10 was highly expressed in advanced stage human UBUCs, suggesting a role for this protein in cancer progression." (PMID 27780919, 2016). "Aberrant MCM10 expression is involved in cancer growth and metastasis." (PMID 40651967, 2025). "Future studies must investigate how the SV40 replisome coordinates with FPC and Mcm10 in vivo, which may help develop molecularly targeted therapies against this broad spectrum of viruses and virus-related cancers." (PMID 38967018, 2024). "Our study also found that MCM10 expression was significantly upregulated in most cancer types, which may contribute to tumorigenesis." (PMID 37848534, 2023). "Overall, using a variety of techniques, we determined the importance of MCM10 in pan-cancer." (PMID 37848534, 2023). "The precise biochemical mechanism through which MCM10 promotes cancer is still a mystery." (PMID 37848534, 2023). "After that, we investigated the correlation between pan-cancer patient OS and MCM10 expression." (PMID 37848534, 2023). "In conclusion, MCM10 may be a desirable pan-cancer biomarker and offer fresh perspectives on cancer therapy." (PMID 37848534, 2023). "Taken together, MCM10 methylation is dysregulated in several cancer types." (PMID 37848534, 2023). "Thus, the level of MCM10 plays a crucial role in compensating for DNA replication stress in cancer cells and facilitates genome duplication in S-phase by firing additional origins that are primed and licensed to fire." (PMID 39086679, 2023). "We speculate that MCM10 is an oncogene in a number of cancer types and might thus be employed as a prognostic marker in light of our findings." (PMID 37848534, 2023). "This shows that MCM10 acts as a limiting factor for dealing with origin activation in cancer cells." (PMID 39086679, 2023). "Previous studies suggested that MCM10 may be part of a high-priority group of genes that may promote cell cycle-related processes in cancer cells." (PMID 35664337, 2022).
cancer (continued). "However, the mechanism by which MCM10 drives genomic instability and cancer progression remains unexplored." (PMID 35813483, 2022). "However, under pathological conditions, MCM10 is frequently deregulated, and gene amplification and overexpression are very common in cancer." (PMID 35664337, 2022). "This implies that aberrant expression of MCM10 may contribute to impaired replication and abnormal proliferation, which might lead to genomic instability and cancer development or progression." (PMID 35813483, 2022). "Moreover, we overlapped the results from this REC analysis with the relationships between basal cell-line expression of MCM2 or MCM10 to drug sensitivity data obtained from the Cancer Therapeutics Response Portal (CTRP) data set." (PMID 35056094, 2021). "This was accomplished by screening MCM10’s role in several organotypic cancers." (PMID 33604163, 2021). "Importantly, MCM10 is shown to be served as a promising prognostic biomarker and MCM10 inhibitors Suramin, and its analogues are revealed to present potential anti‐cancer effects for ESCC." (PMID 34185429, 2021). "Second, aberrant overexpression of MCM10 might act as an augmenting force in cancer development or progression to drive over‐replication and genomic instability." (PMID 34185429, 2021). "The protein levels of CHEK1 and MCM10 were more significant in carcinomas than normal tissues and the differential expressions of KIF23 and TTK could be observed between primary lesions and liver metastases." (PMID 33134313, 2020). "Many studies have reported MCM10 overexpression in a variety of cancer types." (PMID 31409229, 2019). "Taken together, Mcm10 appears to be a promising anti-cancer drug target." (PMID 31409229, 2019). "Suramin and its analogues represent the first reported inhibitors of Mcm10 and these compounds may lead to the development of higher potency and more selective small molecules with improved physico-chemical properties targeting Mcm10 to treat cancer." (PMID 31409229, 2019). "There is accumulating evidence that Mcm10 plays an important role in cancer development." (PMID 31409229, 2019). "Hence, studies on post-translational regulation of MCM10 are required to analyze the activation and initiation mechanism of MCM10 during cancer." (PMID 30135378, 2018). "Although the exact mechanism on regulation of MCM10 is still unknown, high expression of MCM10 can serve as an indicator of cancer progression." (PMID 30135378, 2018). "Based on recent studies, future investigations into Mcm10’s relationship with cancer development and progression could lead to discoveries with significant prognostic and even therapeutic value." (PMID 28218679, 2017). "Additional cell cycle related transcripts, including other MCM genes, are also upregulated in these cancer samples, suggesting that enhanced Mcm10 production may simply coincide with increased DNA synthesis." (PMID 28218679, 2017). "Future investigations should determine whether early detection of increased Mcm10 production has prognostic value in other cancer types." (PMID 28218679, 2017). "Taken together, these data clearly show that mcm10 is altered in cancer genomes." (PMID 28218679, 2017). "Several studies have found MCM10 expression to be significantly upregulated in cancer cells." (PMID 28218679, 2017). "Future evaluations of this hypothesis will be crucial to understanding Mcm10’s contribution to cancer development." (PMID 28218679, 2017). "Interestingly, it was reported that the depletion of MCM10 by small interfering RNA in cancer cells accumulates DNA damage and arrests the cells in late S-G2 phase, suggesting a role for MCM10 in cell cycle checkpoints." (PMID 19500427, 2009). "The upregulated expression of MCM10 in cancer cells may suggest its potential implication in TMM." (PMID 38763334, 2024).
cancer (continued). "We found seven upregulated genes (MCM10, RAD51-associated protein 1 (RAD51AP1), KIF2C, Y_RNA, FAM64A, CDC6, and CDCA8) and six downregulated genes (ADAMTS8, ATP1A2, MYH1, OGN, OMD, and ZBTB16) in at least two phenotypes containing either ALT high/middle or TEL high/middle regardless the cancer type." (PMID 38763334, 2024). "Of the MCM protein family, MCM10 is a crucial member that maintains the stability and extension of DNA replication forks during DNA replication and is significantly overexpressed in a variety of cancer tissues, regulating the biological behaviour of cancer cells." (PMID 37848534, 2023). "Notably, MCM10 is highly expressed in almost all cancer types." (PMID 37848534, 2023). "Therefore, our pan-cancer analysis based on data from public databases suggests that MCM10 may act as a novel prognostic biomarker as well as a potential therapeutic target." (PMID 37848534, 2023). "Therefore, future researches on Mcm10’s relationship to cancer development and progression may lead to discoveries with momentous prognostic and even therapeutic value." (PMID 35664337, 2022). "Thus, MCM10 expression levels could be one of the barriers in preventing replication catastrophe that may lead to genomic instability and cancer development/progression." (PMID 35813483, 2022). "Thus, MCM10 could act as both, a potential clinical marker to detect the active degree of BC malignancies and a capable therapeutic target for future cancer therapy." (PMID 35813483, 2022). "MCM10 plays an important role in assembly of complex during DNA replication and its unbalance with other factors broken by DNA damage might contribute to the initiation of cancer." (PMID 33134313, 2020). "Given that MCM10 has been identified as a key suppressor of DNA damage in several studies, including two independent genome-wide screens, it has been hypothesized that cancer cells rely on high levels of Mcm10 to promote growth and reduce genome instability." (PMID 31409229, 2019). "Moreover, suramin, NF157 and NF546 may preferentially kill cancer cells by blocking Mcm10-dependent DNA replication." (PMID 31409229, 2019). "These would suggest that MCM10 expression levels impact TMB and MSI in cancer, which in turn affects how well a patient responds to immune checkpoint inhibitor medication." (PMID 37848534, 2023). "Mechanically, increased expression of MCM10 plays a vital role in inducing proliferation and accumulating ssDNA without activating the DDR, resulting to replication catastrophe and cancer development." (PMID 35813483, 2022). "Interestingly, there were only a few mutations within the data set, suggesting that while MCM10 may be correlated with cancer pathogenesis, it may not be the leading cause." (PMID 33604163, 2021). "In our study, we also indicated that the MCM10 inhibitors Suramin and its analogues (NF157, NF546, and PPADS) can block both cancer cells proliferation and migration in the ESCC." (PMID 34185429, 2021). "We furthermore discovered 5 genes (MDGA1, VEGFC, MCM10, CTBP1-DT, CHMP4A) with three OS correlations, and 22 genes with two OS correlations, across eight cancer types." (PMID 32764426, 2020). "Searching for other proliferation genes resulted in finding EXO1, MCM10, GINS2, CDT1, ORC6L, and BLM had the same pattern indicating they are most likely necessarily highly transcribed in cancer." (PMID 31857847, 2019). "MCM10 mRNA expression was significantly upregulated in higher stage tumors in both UTUC (P=0.001) and UBUC (P=0.004) tissue, suggesting its role in cancer progression." (PMID 27780919, 2016). "For further exploration, we selected five genes that have been previously experimentally demonstrated in other cancer setting in humans, CXCL8/IL8, UHRF1, BRCA1, MCM10, and CDKN3." (PMID 26859141, 2016). "We selected the overlapped genes-PLK1, MCM2, MCM3, MCM7, MCM10 (ranked 13 by NGP-NR in NSCLC patient datasets) and SKP2 to investigate their functions in cancer." (PMID 22838965, 2012).